AR (androgen receptor)
Diseases named in the same sentence as AR in open-access papers (continued):
Sharing a sentence is not in itself a finding about the gene and the disease.
breast carcinoma (continued). "Our findings here suggest an independent role for AR in AR+/ER+ breast cancer models in response to radiation compared to the previously established role for AR in the radiation response in AR+/ER− (TNBC) models and other AR+ cancers." (PMID 35618789, 2022). "Collectively, these results suggest that Kindlin-2 is critical for regulation of AR signaling, breast cancer cell proliferation and migration." (PMID 35595729, 2022). "By contrast, the AR agonist dihydrotestosterone has been reported to inhibits metastasis of ER-Y537S or ER-D538G breast cancer cells in vivo." (PMID 36198774, 2022). "In AR+ breast cancer cells, USP14 inhibition can induce poly (ADP-ribose) polymerase 1 (PARP) cleavage and suppress BCL2 protein expression." (PMID 35884607, 2022). "To explore the importance of ACK1 and AR in breast cancer, we analyzed their expression in a panel of 14 human breast cancer cell lines and 13 human breast cancer tissues by Western blot assay." (PMID 35768871, 2022). "The PI3K pathway has been revealed to contribute to breast cancer development, while the combined inhibition of AR and PI3K significantly suppressed cell propagation in cell models." (PMID 35053220, 2022). "AR pathway activity and AR expression are also found to be positively correlated in HER2-positive breast cancer and inversely correlated in HER2-negative breast cancer." (PMID 35207749, 2022). "Androgens play a crucial role in female development and physiology, and a vast majority of breast cancers (BC) are positive for AR." (PMID 35163477, 2022). "AR positive primary breast cancer is characterized by increased AR expression and a hormone-driven transcription program." (PMID 36045397, 2022). "Accumulating evidence suggests that the androgen receptor (AR) and its endogenous ligands influence disease progression in breast cancer (BCa)." (PMID 35568821, 2022). "In ER+ PR+ breast cancers, AR dimers translocate to the nucleus, compete with ERα and PR to bind estrogen–responsive elements, and block ER–mediated signaling pathways." (PMID 36556209, 2022). "More extensive and in–depth studies are further needed to address the relationship between luminal B breast cancer and AR." (PMID 36556209, 2022). "While AR expression was more prevalent in breast cancer than ER, the detailed molecular role of AR in breast cancer remains unresolved." (PMID 36232774, 2022). "Breast cancer is hormone-dependent, and cancerous breast tissue promotes mitosis by expressing ER, AR, and PR receptors." (PMID 35281118, 2022). "In TNBC, AR positivity is associated with a poor response to neoadjuvant therapy, whereas in HER–2–positive breast cancer, AR expression suggests a good response to neoadjuvant therapy." (PMID 36556209, 2022). "Androgen receptor expression and function have important implications on proliferation, tumor progression, immunity and molecular signaling in breast cancer." (PMID 35203574, 2022). "Androgen receptor expression and positivity is emerging as a possible prognostic indicator of early breast cancer." (PMID 35711833, 2022). "Meanwhile, PTEN, a negative regulator of PIP3 signaling, is transcriptionally activated by AR in breast cancer." (PMID 35203574, 2022). "To test this, we carried out sequential immunoprecipitation (IP) experiments with either anti-Kindlin-2 or anti-AR antibodies in breast cancer cells." (PMID 35595729, 2022). "The expression of AR in TNBC seemed to make the prognosis more favorable like the endocrine sensitive breast cancer subtypes." (PMID 35711833, 2022). "It is essential to understand the role of AR in ER-positive and ER-negative breast cancer for the precise application of SARMs in breast cancer." (PMID 36232774, 2022). "Several MYC-driven multiple myeloma cells and oestrogen receptor- and/or AR-positive breast cancer cells were also acutely sensitive to AU-15330." (PMID 34937944, 2022).
breast carcinoma (continued). "Individual transcripts with the most significant changes in AA patients included AR and GFRA1, which have been previously implicated in Pan-Gyn malignancies and breast cancer, respectively." (PMID 35992327, 2022). "Several studies have explored the role of activated AR in breast cancer initiation and progression, and in the regulation of transcription of EMT-regulatory genes." (PMID 36584207, 2022). "Since anti-androgen therapy is a relatively safe treatment with manageable side effects, AR remains a potential target for breast cancer." (PMID 35711833, 2022). "As a result of the low AR expression in breast cancer patients, [18F]FDHT-PET showed relatively lower visual agreement than [18F]FES in this study." (PMID 35565232, 2022). "AR > 78% has been shown to predict the survival of ERα-positive patients, and AR > 35% has been shown to predict RFS in patients with surgically resected breast cancer." (PMID 35207749, 2022). "Their findings showed that high AR mRNA levels were generally common among HER–2–overexpressing breast cancers and luminal–type breast cancers but extremely rare in TNBC." (PMID 36556209, 2022). "ER-positive breast cancers are significantly more likely to be AR-positive than ER-negative tumours, with some studies suggesting AR status is a correlate of ER-alpha/PgR signaling." (PMID 35512428, 2022). "The androgen receptor is a member of the steroid nuclear receptor superfamily, and it is widely expressed in different subtypes of breast cancer, including HER2+ tumors." (PMID 35052843, 2022). "The androgen receptor plays a significant role in the development of breast cancers, whereas its therapeutic value seems to be controversial and needs further study." (PMID 35800434, 2022). "The expression and transcriptional regulation of the AR in breast cancer cells, including MCF-7 cells, has been known, and the crosstalk between ERα and the AR in breast cancer progression is a likely mechanism of transcriptional regulation of these two genes." (PMID 35976950, 2022). "We show here that Kindlin-2, a focal adhesion protein, is critically involved in the promotion of AR signaling and breast cancer progression." (PMID 35595729, 2022). "The encouraging results from targeting AR in prostate cancer have provided proof of concept for its application in breast cancers, including TNBC." (PMID 36612226, 2022). "Further studies of the androgen receptor (AR) in breast cancer have demonstrated its role in chromatin binding." (PMID 35158742, 2022). "To examine which site of tyrosine phosphorylation was regulated by Kindlin-2, we analyzed the effect of Kindlin-2 on Tyr-267 and Try-534 phosphorylation of AR in two AR-positive human breast cancer cell lines, BT549 and MDA-MB-453, respectively." (PMID 35595729, 2022). "Fluoxymesterone, also known as CR1447 or 4-hydroxytestosterone (4-OHT), is an androgen receptor modulator that exerts antiproliferative effects in ER + ve and ER-ve/AR+ ve breast cancer cells." (PMID 36612226, 2022). "Activated AR, on the other hand, inhibited the growth of breast cancers driven by the ER through displacement of the ER and critical transcriptional co-activators from chromatin, which resulted in transcriptional downregulation." (PMID 36744180, 2022). "Human breast cancer samples that showed immunoreactions to Arom were mainly ERα+, but showed low counts of AR TS." (PMID 36006309, 2022). "This concept was initially studied in the phase II Translational Breast Cancer Research Consortium (TBCRC 011) trial that explored the role of bicalutamide among androgen receptor (AR)-positive, ER- and PR-negative metastatic breast cancer." (PMID 35877237, 2022). "About 70–80% of all breast cancer is AR-positive, and AR has emerged as a possible target for breast cancer therapy." (PMID 35565232, 2022). "Like the ER, AR is a member of the steroid-hormone receptor superfamily and can be expressed in high concentrations on breast cancer tissue." (PMID 35512428, 2022).
breast carcinoma (continued). "Among them, activation of AR has been increasingly recognized as a key event in breast cancer progression." (PMID 35595729, 2022). "Although the role of AR remains controversial, it is nevertheless an attractive candidate for developing novel breast cancer therapies, potentially improving breast cancer patients’ survival outcomes." (PMID 35054486, 2022). "ACSL4 catalyzes long chain fatty acid activation for the support of metabolic processes, and its expression in breast cancer is inversely correlated with the expression of AR in addition to that of ER, PR and HER2." (PMID 35203574, 2022). "The potential therapeutic use of these agents, including second-generation anti-androgens apalutamide (ARN-509), darolutamide (ODM-201) and enzalutamide (MDV3100), has been explored in other AR+ cancers, including AR+ breast cancers." (PMID 35618789, 2022). "The pathophysiology of prostate and breast cancer demonstrated an androgen receptor (AR) and estrogen receptor-α hormonal interventions, respectively." (PMID 36432713, 2022). "Many studies have reported that positive AR expression is a good prognostic marker and is related to favorable clinical outcomes in breast cancer." (PMID 36178912, 2022). "Since breast cancers are molecularly heterogeneous, and the growth of the tumor results from the contribution of various molecules, the role of AR in breast cancers needs to be discussed separately for the different sub-types." (PMID 35053220, 2022). "With increasing evidence to support that AR plays an essential role in breast cancer, AR has been considered a useful biomarker in breast cancer, depending on the context of breast cancer sub-types." (PMID 35053220, 2022). "Nuclear TTP acts as a corepressor of steroid nuclear receptors (i.e., ERα, PR, GR, and AR) in breast cancer cells." (PMID 35265093, 2022). "The expression of ER is related to the prognosis of breast cancer, so it is necessary to consider the impact of ER on the relationship between AR/ER and prognosis." (PMID 36556209, 2022). "Triple negative breast cancer is now known to be a heterogeneous disease that is currently classified into the basal-like 1, basal-like 2, mesenchymal-like and AR positive molecular subtypes." (PMID 36230969, 2022). "The androgen receptor pathway is emerging as a potential therapeutic target in breast cancer, and AR-targeted treatment for breast cancer is an area of active investigation." (PMID 35954393, 2022). "AR has also been shown to be predictive of the potential of response to adjuvant hormonal therapy in ER + ve breast cancers and to neoadjuvant chemotherapy in TNBC." (PMID 35053220, 2022). "Over 80% of breast cancer patients have ER-positive (ER+) tumours that express ER, and the androgen receptor (AR) is co-expressed with the estrogen receptor in 70–95% of all ER+ breast cancers." (PMID 35618789, 2022). "To further test this, we assessed the effects of Kindlin-2 knockdown on the transcription of cyclin D1, a well-known AR target gene that promotes breast cancer progression and metastasis." (PMID 35595729, 2022). "The interplay of ER and AR would suggest in this breast cancer patients that would likely benefit from both the antitumor and the anti-COVID-19 effects." (PMID 35399920, 2022). "Depletion of Kindlin-2 was sufficient to suppress Src-mediated AR Tyr-534 phosphorylation and signaling, resulting in diminished breast cancer cell proliferation and migration." (PMID 35595729, 2022). "In HER2-positive breast cancer cells, AR promotes the expression of the HER3 gene, and the HER2/HER3 heterodimer activates the PI3K/AKT pathway and the MYC gene and promotes cell proliferation." (PMID 35207749, 2022). "For instance, a prospective cohort study showed that the immunohistochemical AR status in primary breast carcinoma tissues correlates with longer disease-free survival in the patients treated with AIs." (PMID 37435447, 2022).
breast carcinoma (continued). "The role of AR is complex in breast cancer: AR possesses anti-tumor activity in estrogen receptor positive (ER+) breast cancer." (PMID 35768871, 2022). "The breast cancer samples were divided into AR-high and AR-low groups using the expression value of the AR gene." (PMID 36232774, 2022). "AR has also been shown to facilitate ER chromatin binding and AR inhibition reduced estradiol-mediated proliferation in ER+/AR+ breast cancer cell lines and synergized with tamoxifen and fulvestrant." (PMID 35774123, 2022). "Most studies have used 10% as the cutoff for AR positivity as recommended by the College of American Pathology previously for the estrogen/progesterone receptors in breast cancer before the change of cutoff to 1%." (PMID 35711833, 2022). "The phase II study exploring bicalutamide has proved that antiandrogen therapy is effective in treating patients with AR positive breast cancer." (PMID 35243562, 2022). "Expression of the androgen receptor (AR) in breast cancer is even less studied, although in recent years research on AR expression has been increased for its prognostic value and as a potential therapeutic target for triple-negative breast cancer." (PMID 36006309, 2022). "The expression of AR was related to a good prognosis in early breast cancer in terms of both disease-free survival and overall survival." (PMID 36232774, 2022). "Although abiraterone is currently clinically used in the treatment of prostate cancer, with the in-depth study of AR expression in breast cancer, it has a theoretical prospect of application in the treatment of breast cancer." (PMID 35311116, 2022). "ER crosstalk with both PR and AR are the best-characterized models of nuclear receptor interactions in breast cancer, but lately, the interaction of ER with GR has been emerged." (PMID 35761157, 2022). "The androgen receptor (AR) can be detected in most breast cancers, but both its expression level and prognostic effect vary." (PMID 35207749, 2022). "In these subtypes, AR regulates a transcriptional program similar to ERα in luminal breast cancer cells." (PMID 37435447, 2022). "A recent study showed that macrophages express AR and play pivotal roles in human diseases, including breast cancers." (PMID 37435447, 2022). "Similar to ERα-positive breast cancers, AR status correlates with better clinical outcomes, but the tendency seems to be less clear than in ERα-positive cancers." (PMID 37435447, 2022). "Since DHT promotes cell metastasis via activating AR in breast cancer, we next examined the effects of HC-1119 treatment on the migration and invasion of these cells." (PMID 35960413, 2022). "Recently, the androgen receptor has been found as a potential prognostic index and therapeutic target for breast cancer." (PMID 35800434, 2022). "The androgen receptor is the only sex steroid receptor that plays a cardinal role in the progression of breast cancers and is typically overexpressed in LAR." (PMID 36612226, 2022). "The suitable electronic sources used in the current review were identified from the PubMed database by searching the following key words: breast cancer; androgen receptor; targeted therapy; prognosis." (PMID 36499670, 2022). "Using context-dependent and physiologically relevant anti-cancer stress in PCA or breast cancer cells, this study shows that AR or ER mRNA support the formation of SGs under specific stress of AR or ER antagonism." (PMID 34939643, 2022). "Antiandrogen therapy has successfully been used for treating metastatic AR positive male breast cancer." (PMID 36405944, 2022). "combined the AR inhibitor Enzaruamide with endocrine therapy to treat breast cancer and found that it had a good effect." (PMID 35311116, 2022). "Combination therapy of these drugs were investigated using AR positive breast cancer mouse xenograft models." (PMID 35768871, 2022).
breast carcinoma (continued). "AR has been shown to compete with ER for binding to estrogen response elements (EREs) therefore acting as an antagonist to ER signaling in AR+/ER+ breast cancers." (PMID 35618789, 2022). "There is a substantial variability in the frequency of AR expression in breast cancer of various subtypes including TNBC, with a wide range of 6.6%–75%." (PMID 36405944, 2022). "This review will mainly focus on discussing the use of androgen receptor (AR) as a prognostic and predictive biomarker for breast cancer management and treatment." (PMID 35053220, 2022). "Breast cancer cases with AR expression in the upper tertile were included in the AR-high group and those in the lower tertile were included in the AR-low group." (PMID 36232774, 2022). "These tumours, accounting for 10% of TNBCs, constitute a distinct subgroup with increased expression of AR mRNA and many gene expression features of ER positive luminal breast cancer." (PMID 34537861, 2022). "It is generally accepted that 70–90% of patients with luminal–type breast cancer are positive for AR expression." (PMID 36556209, 2022). "Contrary to the PCA3 promoter, the PSA chimeric promoter, PSEBC, was highly androgen responsive in AR-expressing PCa cell lines and it was also active in AR-expressing breast cancer cells such as CAMA-1 and ZR-75-1." (PMID 34976196, 2022). "Other steroidal Nuclear Receptors (NRs), such as the Progesterone Receptor (PR) and the Androgen Receptor (AR), play a role in breast cancer." (PMID 35160139, 2022). "Studying AR signaling pathway can not only reflect the severity of the disease, but also provide ideas for the treatment of breast cancer." (PMID 35311116, 2022). "An earlier study reported AR positivity in 100% of gynaecomastia samples, compared to 87% positivity in male breast carcinoma." (PMID 35814372, 2022). "Suppression of POLR3G activates the expression of FOXA1 and androgen receptor, two key factors that are characteristic of luminal and molecular apocrine breast cancers in which they contribute to controlling hormone response and can be targeted for therapies." (PMID 36497214, 2022). "Among the most negatively enriched pathways was androgen signalling, which would be consistent with the reported estrogen-mediated reductions in AR levels in breast cancer cells." (PMID 36198774, 2022). "Some studies also revealed more favorable overall survival (OS) and breast cancer-specific survival (BCSS) for patients with AR-positive triple-negative APO compared with other triple-negative breast carcinomas (TNBC)." (PMID 35355162, 2022). "In order to choose appropriate breast cancer cell lines for this study, we examined ER, PR, HER2 and AR expression in multiple breast cancer cell lines." (PMID 35960413, 2022). "The existing survival analyses suggest that AR acts as a tumor suppressor in ER + ve breast cancers, serving as a favorable prognostic marker." (PMID 35053220, 2022). "The AR is expressed in 70–90% of breast cancer cases, and today we know that this receptor plays an essential role in breast cancer pathology and development." (PMID 36548336, 2022). "Despite being anti-proliferative in ER+ breast cancer by inhibiting ERα signaling, the AR promotes cell proliferation in ER-breast cancers." (PMID 35884607, 2022). "There are some reviews that have summarized the physiology of ARs, the mechanisms involved, and AR-targeted therapies in breast cancers." (PMID 35800434, 2022). "Inhibition of USP14 resulted in suppressed AR-responsive (AR+) breast cancer cell proliferation by G0/G1 cell cycle arrest." (PMID 35884607, 2022). "Given the tremendous success of targeting estrogen in breast cancer, AR represents a possible therapeutic target in TNBCs and chemoresistant breast cancers, which have an otherwise inferior prognosis." (PMID 36584207, 2022). "The first ten keywords emphasize the emerging trend of the research between breast cancer and androgen receptor in 2011–2015." (PMID 35800434, 2022).